EP300 (EP300 lysine acetyltransferase)
Description:
Functions as a histone acetyltransferase and regulates transcription via chromatin remodeling. Acetylates all four core histones in nucleosomes. Histone acetylation gives an epigenetic tag for transcriptional activation. Mediates acetylation of histone H3 at 'Lys-122' (H3K122ac), a modification that localizes at the surface of the histone octamer and stimulates transcription, possibly by promoting nucleosome instability. Mediates acetylation of histone H3 at 'Lys-18' and 'Lys-27' (H3K18ac and H3K27ac, respectively). Also able to acetylate histone lysine residues that are already monomethylated on the same side chain to form N6-acetyl-N6-methyllysine (Kacme), an epigenetic mark of active chromatin associated with increased transcriptional initiation. Catalyzes formation of histone H4 acetyl-methylated at 'Lys-5' and 'Lys-12' (H4K5acme and H4K12acme, respectively). In response to DNA damage, catalyzes acetylation of histone H1 at 'Lys-75' (H1K75ac) following histone H1 deamidation by CTPS1, increasing chromatin accessibility to facilitate the recruitment of DNA repair proteins. Also functions as acetyltransferase for non-histone targets, such as ALX1, HDAC1, PRDM16, PRMT1, SIRT2, STAT3, ZNF76 or GLUL. Acetylates 'Lys-131' of ALX1 and acts as its coactivator. Promotes chromatin acetylation in heat shock responsive HSP genes during the heat shock response (HSR), thereby stimulating HSR transcription. Acetylates HDAC1 leading to its inactivation and modulation of transcription. Acetylates 'Lys-247' of EGR2 (By similarity). Acts as a TFAP2A-mediated transcriptional coactivator in presence of CITED2. Plays a role as a coactivator of NEUROD1-dependent transcription of the secretin and p21 genes and controls terminal differentiation of cells in the intestinal epithelium. Promotes cardiac myocyte enlargement. Can also mediate transcriptional repression. Acetylates FOXO1 and enhances its transcriptional activity. Acetylates STAT3 at different sites, promoting both STAT3 dimerization and activation and recruitment to chromatin. Acetylates BCL6 which disrupts its ability to recruit histone deacetylases and hinders its transcriptional repressor activity. Participates in CLOCK or NPAS2-regulated rhythmic gene transcription; exhibits a circadian association with CLOCK or NPAS2, correlating with increase in PER1/2 mRNA and histone H3 acetylation on the PER1/2 promoter. Acetylates MTA1 at 'Lys-626' which is essential for its transcriptional coactivator activity. Acetylates XBP1 isoform 2; acetylation increases protein stability of XBP1 isoform 2 and enhances its transcriptional activity. Acetylates PCNA; acetylation promotes removal of chromatin-bound PCNA and its degradation during nucleotide excision repair (NER). Acetylates MEF2D. Acetylates and stabilizes ZBTB7B protein by antagonizing ubiquitin conjugation and degradation, this mechanism may be involved in CD4/CD8 lineage differentiation. Acetylates GABPB1, impairing GABPB1 heterotetramerization and activity (By similarity). Acetylates PCK1 and promotes PCK1 anaplerotic activity. Acetylates RXRA and RXRG. Acetylates isoform M2 of PKM (PKM2), promoting its homodimerization and conversion into a protein kinase. Acetylates RPTOR in response to leucine, leading to activation of the mTORC1 complex. Acetylates RICTOR, leading to activation of the mTORC2 complex. Mediates cAMP-gene regulation by binding specifically to phosphorylated CREBBP. In addition to protein acetyltransferase, can use different acyl-CoA substrates, such as (2E)-butenoyl-CoA (crotonyl-CoA), butanoyl-CoA (butyryl-CoA), 2-hydroxyisobutanoyl-CoA (2-hydroxyisobutyryl-CoA), lactoyl-CoA, propanoyl-CoA (propionyl-CoA) or isonicotinyl-CoA, and is able to mediate protein crotonylation, butyrylation, 2-hydroxyisobutyrylation, lactylation, propionylation or isonicotinylation, respectively. Acts as a histone crotonyltransferase; crotonylation marks active promoters and enhancers and confers resistance to transcriptional repressors. Histone crotonyltransferase activity is dependent on the concentration of (2E)- butenoyl-CoA (crotonyl-CoA) substrate and such activity is weak when (2E)-butenoyl-CoA (crotonyl-CoA) concentration is low. Also acts as a histone butyryltransferase; butyrylation marks active promoters. Catalyzes histone lactylation in macrophages by using lactoyl-CoA directly derived from endogenous or exogenous lactate, leading to stimulates gene transcription. Acts as a protein-lysine 2-hydroxyisobutyryltransferase; regulates glycolysis by mediating 2-hydroxyisobutyrylation of glycolytic enzymes. Functions as a transcriptional coactivator for SMAD4 in the TGF-beta signaling pathway. (Microbial infection) In case of HIV-1 infection, it is recruited by the viral protein Tat. Regulates Tat's transactivating activity and may help inducing chromatin remodeling of proviral genes. Binds to and may be involved in the transforming capacity of the adenovirus E1A protein.
Synonyms: P300; KAT3B; MKHK2; RSTS2
Tractability: Small molecule: a structure with a bound ligand is known; a high-quality ligand is known; it has a high-quality binding pocket; it belongs to a druggable protein family. PROTAC: UniProt records ubiquitination sites on it; ubiquitination databases record sites on it; its protein half-life has been measured; a small molecule that binds it is known.
Target class: Epigenetic regulator; Histone acetyltransferase; p300/CBP family; Writer
Chemical probes: A-485 (high quality), CPI-1612 (high quality), CPI-637 (high quality), GNE-049 (high quality), GNE-781 (high quality), I-CBP112 (high quality), PF-CBP1 (high quality), SGC-CBP30 (high quality)
Gene: Protein-coding gene on chromosome 22 (41,091,816 to 41,180,077, forward strand). Ensembl gene ENSG00000100393.
Subcellular location: Cytoplasm; Nucleus; Chromosome
Subcellular location (Human Protein Atlas): Nucleoplasm; Centrosome; Cytosol
Pathways (Reactome):
Gene expression (Transcription): Activation of the TFAP2 (AP-2) family of transcription factors; B-WICH complex positively regulates rRNA expression; FOXO-mediated transcription of cell death genes; MLL4 and MLL3 complexes regulate expression of PPARG target genes in adipogenesis and hepatic steatosis; RUNX1 interacts with co-factors whose precise effect on RUNX1 targets is not known; RUNX1 regulates genes involved in megakaryocyte differentiation and platelet function; RUNX3 regulates NOTCH signaling; RUNX3 regulates p14-ARF; Regulation of FOXO transcriptional activity by acetylation; Regulation of RUNX3 expression and activity
Signal Transduction: Estrogen-dependent gene expression; Formation of the beta-catenin:TCF transactivating complex; NGF-stimulated transcription; NOTCH1 Intracellular Domain Regulates Transcription; NOTCH2 intracellular domain regulates transcription; NOTCH3 Intracellular Domain Regulates Transcription; NOTCH4 Intracellular Domain Regulates Transcription; NR1H3 & NR1H2 regulate gene expression linked to cholesterol transport and efflux; Pre-NOTCH Transcription and Translation; SMAD2/SMAD3:SMAD4 heterotrimer regulates transcription; STAT3 nuclear events downstream of ALK signaling; TGFBR3 expression
Cellular responses to stimuli: Attenuation phase; Heme signaling; NFE2L2 regulates pentose phosphate pathway genes; NFE2L2 regulating ER-stress associated genes; NFE2L2 regulating MDR associated enzymes; NFE2L2 regulating anti-oxidant/detoxification enzymes; NFE2L2 regulating inflammation associated genes; NFE2L2 regulating tumorigenic genes; Nuclear events mediated by NFE2L2; Regulation of NFE2L2 gene expression; Regulation of gene expression by Hypoxia-inducible Factor
Developmental Biology: Activation of anterior HOX genes in hindbrain development during early embryogenesis; Differentiation of naive CD4+ T cells to T helper 2 cells (Th2 cells); Formation of paraxial mesoderm
and 22 more pathways
Gene Ontology:
Molecular function: acetylation-dependent protein binding; acetyltransferase activity; acyltransferase activity; beta-catenin binding; chromatin binding; damaged DNA binding; DNA binding; DNA-binding transcription factor binding; histone acetyltransferase activity; histone crotonyltransferase activity; histone H1K75 acetyltransferase activity; histone H2B acetyltransferase activity; histone H3 acetyltransferase activity; histone H3K122 acetyltransferase activity; histone H3K18 acetyltransferase activity; histone H3K27 acetyltransferase activity; histone H4 acetyltransferase activity; histone isonicotinyltransferase activity; histone lactyltransferase (CoA-dependent) activity; L-lysine N-acetyltransferase activity, acting on acetyl phosphate as donor; NF-kappaB binding; nuclear androgen receptor binding; nuclear receptor binding; peptide 2-hydroxyisobutyryltransferase activity; peptide butyryltransferase activity; and 17 more
Biological process: apoptotic process; canonical NF-kappaB signal transduction; canonical Wnt signaling pathway; cellular response to L-leucine; cellular response to nutrient levels; DNA repair-dependent chromatin remodeling; host-mediated activation of viral transcription; internal peptidyl-lysine acetylation; internal protein amino acid acetylation; negative regulation of autophagy; negative regulation of chromosome condensation; negative regulation of gluconeogenesis; negative regulation of protein oligomerization; negative regulation of protein-containing complex assembly; negative regulation of transcription by RNA polymerase II; peptidyl-lysine butyrylation; peptidyl-lysine crotonylation; peptidyl-lysine propionylation; positive regulation of DNA-templated transcription; positive regulation of neuron projection development; positive regulation of protein import into nucleus; positive regulation of receptor signaling pathway via JAK-STAT; positive regulation of T-helper 17 cell lineage commitment; positive regulation of TORC1 signaling; and 30 more
Cellular component: chromatin; chromosome; cytoplasm; cytosol; nucleoplasm; nucleus; histone acetyltransferase complex; protein-DNA complex; transcription regulator complex; protein-containing complex
Genetic constraint (gnomAD): Loss-of-function variants: 30 observed, 247.72 expected, observed/expected ratio (o/e) 0.12, 90% interval 0.09 to 0.16. The synonymous counts are far from expectation, so gnomAD's model fits this gene poorly and the ratio says little. Missense variants: 2,688 observed, 3,094.9 expected, observed/expected ratio (o/e) 0.87, 90% interval 0.84 to 0.9. Synonymous variants: 1,292 observed, 1,067.1 expected, observed/expected ratio (o/e) 1.21, 90% interval 1.16 to 1.27.
Gene-disease validity (ClinGen):
ClinGen rates the evidence that EP300 causes each of these diseases.
Rubinstein-Taybi syndrome due to EP300 haploinsufficiency (autosomal dominant): Definitive. Any Rubinstein-Taybi syndrome in which the cause of the disease is a mutation in the EP300 gene.
Cancer hallmarks: suppression of growth (promotes); escaping programmed cell death (suppresses)
Homologues: Orthologues: macaque EP300 (99% identical), dog EP300 (97% identical), pig EP300 (96% identical), rabbit EP300 (95% identical), guinea pig EP300 (95% identical), rat Ep300 (94% identical), mouse Ep300 (94% identical), chimpanzee EP300 (90% identical), tropical clawed frog ep300 (75% identical), zebrafish ep300a (63% identical), zebrafish ep300b (62% identical), Drosophila melanogaster nej (44% identical), and 5 more. Paralogues in human: CREBBP (59% identical).
Diseases named in the same sentence as EP300 in open-access papers:
EP300 is named in the same sentence as 410 diseases in open-access papers, as found by Europe PMC text mining. Sharing a sentence is not in itself a finding about the gene and the disease. The quoted sentences say what the papers report.
breast carcinoma (182 papers, 2007 to 2025). "Using machine learning algorithms on multi-omics data from over 6,000 breast cancer patients, we identified six key genes significantly associated with VM and patient risk scores: EP300, PIK3CA, DMXL1, LS, ABL2, and CDK4." (PMID 39165361, 2024). "Mining publicly available datasets, we identified that high expression of EP300 in breast cancer patients was associated with reduced and overall survival, further supporting a role for EP300 expression and activity in facilitating disease progression." (PMID 36864079, 2023). "During long-term follow-up of triple-negative breast cancer patients, EP300-G211S was proved to be a protective factor, which decreased breast cancer-specific mortality and predicted a lower risk for relapses." (PMID 35242279, 2022). "Assessing all tumor entities separately, EP300 downregulation was strongly associated with increased cytolytic activity in almost all cancer entities, except for carcinomas of the breast." (PMID 32523042, 2020). "Specific mutations in EP300 predict a lower risk for relapses and decrease the mortality of breast cancer." (PMID 32012118, 2020). "EP300 mutation has been reported in multiple types of human cancer, including breast cancer and squamous cell carcinoma of the head and neck." (PMID 32012118, 2020). "EP300 has been implicated in cancer biology in general and breast cancer in particular, and has been described as both a tumor suppressor and more recently as an oncogene promoting tumor growth, metastatic potential and CSC phenotype in BC." (PMID 33167919, 2020). "While genes correlating with EP300 in basal breast cancer were associated with stem cell biology and cancer metastasis, EP300 correlated genes in TNBC were associated with growth factor signaling pathways." (PMID 33167919, 2020). "In conclusion, PARP1 directs the transcription of some proliferation and DNA repair genes in breast cancer cells by the ADP-ribosylation of EP300, thereby causing its activation and marking nucleosomes for displacement by BRG1." (PMID 31614656, 2019). "EP300-deficient cells increase their motility and invasive properties, both in colon and breast cancer cells." (PMID 28341962, 2017). "Loss of EP300 heterozygosity has been described in breast carcinomas, somatic EP300 mutations have been identified in several malignancies and EP300-deficient colon carcinoma cells show phenotypic changes characteristic of EMT." (PMID 28341962, 2017). "EP300 has a well-established role as a tumor suppressor gene but has been poorly investigated as a breast cancer-predisposing gene." (PMID 28569218, 2017). "The mutative protein EP300 in breast cancer, which was affected by acetylation, could promote the transmission of upstream signals to its downstream regulator." (PMID 33802957, 2021). "Additionally, the findings of studies show that specific mutations in EP300 predict a lower risk of recurrence and reduce breast cancer mortality." (PMID 34354750, 2021). "As EP300 regulates most of the characteristics associated with these phenotypes, we asked whether EP300 would be downregulated in metaplastic breast cancer." (PMID 28341962, 2017). "Previous studies have implied that high EP300 expression correlates with poor prognosis in hepatocellular carcinoma and breast cancer." (PMID 38256128, 2024). "It has been shown that overexpression of EP300 led to upregulation of mesenchymal and stemness markers, increases in migration, invasion, anchorage-independent growth and drug resistance in a breast cancer cell model." (PMID 39419971, 2024). "Elevated levels of Ajuba not only stimulate breast cancer cell growth but also contribute to tamoxifen resistance, making the Ajuba/DBC1/CBP/EP300 ternary complex a new promising target for breast cancer therapy." (PMID 38914477, 2024). "In cancer, EP300 has been demonstrated as an oncogene promoting tumor growth and metastatic potential, and facilitating cancer stemness in breast cancer." (PMID 36674511, 2023).